ENSG00000283205 (novel protein)
Synonyms: LOC122394732
Gene: Protein-coding gene on chromosome 9 (87,956,214 to 87,956,883, forward strand). Ensembl gene ENSG00000283205.
Homologues: Orthologues: mouse Gm47429 (57% identical).